ERG (ETS transcription factor ERG)
Diseases named in the same sentence as ERG in open-access papers (continued):
Sharing a sentence is not in itself a finding about the gene and the disease.
tumor (continued). "Among others, researchers have linked this molecular feature with increased tumor grade and even increased lethality in patients who underwent radical prostatectomy, with the risk being more pronounced when tumors exhibited a concurrent loss of ERG immunoexpression." (PMID 37185705, 2023). "Furthermore, PITX1 was strongly linked to the presence of ERG fusion: nearly 80% of ERG positive tumor samples (71.6% low and 6.9% high) but only 55% of ERG negative tumor samples (51.5% low and 3.3% high) (p < 0.0001) showed immune-histochemical PITX1 expression." (PMID 35267575, 2022). "The dysregulation of ERG exerts diverse effects by regulating the expression of different downstream genes, which could be associated with the gene regulatory network heterogeneity and tumor progression of CRC." (PMID 34917613, 2021). "Furthermore, intra-tumor differences in ERG alterations may lead to expression of ERG variants, which could be further exacerbated by inter-tumor heterogeneity." (PMID 31741711, 2019). "This supports combining PARP inhibitors with RT for tumor-selective radiosensitization in ERG+ patients." (PMID 41632544, 2026). "Subcutaneous injection of cells from the PC3M model demonstrated that overexpression of ETV1 and ERG induced greater tumour growth than control cells throughout the evaluation process." (PMID 39374163, 2025). "Using lineage tracing, we find the tumor-initiating activity of ERG resides in a subpopulation of murine basal cells that coexpress luminal genes (BasalLum) and not in the larger population of ERG+ luminal cells." (PMID 40858905, 2025). "By using a specific MET tyrosine kinase inhibitor in a humanised hepatocyte growth factor (HGF) mouse model, we also establish that MET activity is required for ETV1/ERG‐mediated tumour growth." (PMID 39374163, 2025). "We performed subcutaneous injection of PC3M Ctrl, ETV1 and ERG cells into both flanks of the mice and monitored tumour growth over one month." (PMID 39374163, 2025). "The expression patterns of PTEN and ERG provide valuable insights into tumour characteristics, patient prognosis, and treatment response promising more tailored and effective therapeutic approaches." (PMID 40165885, 2025). "This subtype exhibits reduced dependence on androgen receptor (AR) signalling compared to ERG-positive tumours, contributing to resistance to AR-targeted therapies such as androgen deprivation therapy (ADT)." (PMID 40165885, 2025). "ERG rearrangements often signal more aggressive disease behavior, while PTEN loss correlates with heightened tumor aggressiveness and resistance to therapies." (PMID 40136571, 2025). "ERG, a transcription factor, is commonly overexpressed due to TMPRSS2-ERG gene fusion and has been linked to aggressive tumor behavior." (PMID 40863209, 2025). "Taken together, our findings suggest that while ERG expression reflects tumor advancement, its utility for predicting BCR is limited." (PMID 40863209, 2025). "We confirmed that ERG was markedly decreased in the posttreatment residual tumor and found that PI3K/AKT activity was significantly increased in the T:E fusion–positive versus –negative posttreatment cases." (PMID 41321318, 2025). "Low BAP1 leads to the accumulation of H2A ubiquitination, reinforcing the PRC1-mediated repression of tumor suppressor genes, thus creating a permissive environment for ERG overexpression and tumor progression." (PMID 40136571, 2025). "ERG rearrangements characterised by ERG expression, are more common in Caucasian men compared to African American and Asian men, and the occurrence of ERG+/PTEN− tumours varies by ethnic group." (PMID 40165885, 2025). "This was confirmed in a very recent article showing that ERG can act as a tumor-suppressor gene or as an oncogene with the opposite results." (PMID 39940843, 2025). "Biologically, ERG rearrangements facilitate oncogenesis by promoting androgen receptor (AR)-regulated transcriptional pathways, which enhance tumour invasion and progression." (PMID 40165885, 2025).
tumor (continued). "Immunohistochemically, tumor cells showed nuclear ERG and CD56 positivity in three out of four patients, consistent with PMTs." (PMID 41182108, 2025). "Although ERG fusions are frequently detected, their direct role in driving tumor aggressiveness remains controversial, with conflicting reports on correlations with clinical outcomes." (PMID 40427518, 2025). "The positive staining for CD31, CD34, and ERG in combination with marked proliferation of the tumor, as expressed by proliferation index Ki-67, and the trajectory of the clinical course were the pointers to the correct diagnosis." (PMID 40255814, 2025). "Available data suggest that ERG and AR collaborate to drive PCa development, with ERG modulating the AR transcriptional program and facilitating the expression of AR target genes that enhance tumour growth and survival." (PMID 40165885, 2025). "Immunohistochemistry typically reveals positivity for CD31, CD34, and ERG (erythroblast transformation-specific related gene), consistent with the vascular origin of the tumor." (PMID 40979823, 2025). "The ERG+/PTEN+ tumour molecular subtype of PCa is characterised by ERG rearrangements, most commonly the TMPRSS2:ERG fusion, and intact PTEN function." (PMID 40165885, 2025). "For instance, African American men demonstrate a higher frequency of PTEN-positive tumours and a reduced occurrence of ERG expression, stressing potential ethnic and genetic variations in PCa." (PMID 40165885, 2025). "Immunohistochemical staining showed tumor cells positive for ERG, CD31, and factor VIII, confirming the vascular origin of the tumor." (PMID 40895865, 2025). "An improved understanding of the particular vulnerabilities of ERG+/PTEN+ tumours is necessary to improve treatment approaches and patient outcomes for patients with this genetic subtype of PCa." (PMID 40165885, 2025). "Therapeutically, AR-targeted treatments, such as abiraterone, enzalutamide, and androgen deprivation therapy (ADT), are efficient against ERG-driven tumours." (PMID 40165885, 2025). "It is noteworthy that tumours with both PTEN loss and ERG expression exhibit distinct clinical characteristics and therapeutic responses, indicating the potential of integrating these biomarkers to enhance personalised treatment strategies." (PMID 40165885, 2025). "ERG expression, on the other hand, was correlated with higher pathological tumor stage, suggesting its relevance in evaluating tumor progression." (PMID 40863209, 2025). "Expression of another AR-driven gene, Tmprss2, was also decreased in these tumor areas with low ERG." (PMID 41321318, 2025). "FET::ETS fusions, including EWSR1::ERG have also been reported in the newly emerging superficial neurocristic FET::ETS fusion tumor." (PMID 40640075, 2025). "Metastatic tumor cells were ERG + in 26% of the cases (36 of 139), suggesting TMPRSS2-ERG fusion gene expression." (PMID 40841830, 2025). "PCNA analysis and quantification showed a downward trend in TKI‐treated control‐ETV1 or ‐ERG mice, which is consistent with a potential reduction in proliferation in the treated tumour and therefore with a reduction in tumour volume." (PMID 39374163, 2025). "These subtypes not only increase prognosis accuracy but also facilitate tailored therapies, like medicines that target ERG-mediated pathways or PI3K/AKT inhibitors for tumours losing PTEN." (PMID 40165885, 2025). "The scATAC-seq findings, as well as the scRNA-seq and lineage tracing studies described earlier, collectively point to the EPC-IM cluster as the cell population where ERG activates a tumor initiation program." (PMID 40858905, 2025). "In alignment with prior single-cell cancer research, ERG+ tumor cells formed distinct clusters per patient, apart from non-malignant epithelial clusters." (PMID 40943497, 2025).
tumor (continued). "To explore the potential immune regulatory role of the ERG gene in the tumor microenvironment, we analyzed the correlation between ERG expression levels and the infiltration levels of 22 immune cell types." (PMID 40741330, 2025). "Despite these challenges, the TMPRSS2:ERG fusion remains a potential therapeutic target due to its specificity to PCa and its overexpression throughout various stages of tumour progression." (PMID 40165885, 2025). "Currently, ERG is one of the best available markers of endothelial differentiation, confirming the vascular origin of the tumor." (PMID 40295306, 2025). "The reversal of all these expectable MTAP associations with tumor phenotype and patient outcome in cancers carrying an TMPRSS2:ERG fusion is the most striking finding of this study." (PMID 40554389, 2025). "For instance, androgen deprivation therapies (ADTs), which reduce androgen levels or prevent AR role, have been reported to reduce ERG expression in TMPRSS2:ERG fusion-positive tumours, thus reducing their oncogenic potential." (PMID 40165885, 2025). "The TMPRSS2:ERG fusion leads to the overexpression of the ERG transcription factor, a key driver of tumour invasion and progression." (PMID 40165885, 2025). "This indicates that YAP serves as an essential intermediate factor in the ERG-mediated transformation of prostate epithelial cells and the invasion of tumor cells." (PMID 39963114, 2025). "Another study confirmed its overexpression in PCa tumours compared to normal counterparts, regulated by the ERG oncogene and androgens and proposed it as a promising drug target in PCa." (PMID 39973042, 2025). "Our results are applicable to other oncogenic ES fusion-proteins driven by EWSR1, as genetic or pharmacological inhibition of C1GALT1 also decreases cell viability and tumor growth of ES cells that harbor an EWSR1::ERG fusion." (PMID 39894896, 2025). "Heatmaps were generated to visualize the expression of MRG and ERG in tumor and adjacent tissues from the TCGA-BRCA dataset." (PMID 38875364, 2024). "This analysis found that ERG- cells show heterogeneity with luminal epithelial cells and differ from ERG+ tumor cells, potentially inducing a characteristic TME response." (PMID 39588373, 2024). "Forced expression of ERG, a transcription factor essential for endothelial homeostasis, restores the angiogenic balance in tumor ECs, thereby inhibiting tumor growth and vascular abnormalities." (PMID 38580870, 2024). "The only exception is cellular fibrous histiocytoma, which can closely resemble EWSR1::SMAD3-rearranged tumor morphologically and regularly show diffuse expression of ERG." (PMID 39264472, 2024). "Another study investigated the order and mutual exclusivity between important genetic events and proposed a progression model composed of two tumor lineages, namely ERG–PTEN and SPOP–CHD1." (PMID 39347576, 2024). "Established early oncogenic driver alterations including ERG gene fusions as well as FOXA1, CDK12, and SPOP mutations were typically present in both the primary tumor and LN metastatic foci." (PMID 38773085, 2024). "Tumor stage pT3 was statistically related to PTEN and SPOP loss of expression (p = 0.012 and p = 0.011), as well as to ERG overexpression and the “triple hit” phenotype (p = 0.051 and p < 0.001)." (PMID 38017230, 2024). "OS was negatively correlated with PLP2+ Tumor EPCs score, ERG was significantly negatively correlated with JUND, and most other modeling genes were positively correlated." (PMID 38482016, 2024). "ERG overexpression is known to inhibit programmed cell death and induce cell transformation and tumor development." (PMID 38674385, 2024). "Adding further information to this context, a recent publication by Kodgule and colleagues showed that ERG binds to GGAA microsatellite enhancers and activates according genes in ETV6-deficient or ETV6::RUNX1-positive tumor cells." (PMID 39202339, 2024).
tumor (continued). "We also noticed that not only ERG but also other genes involved in our classification of T2E fusion status showed a closed relationship with tumor development." (PMID 38331878, 2024). "Immunohistochemical examinations showed that the tumor cells were positive for ERG, CD34, CD31, and vimentin, whereas CK (AE1/AE3), EMA, CK7, HMB45, SMA, CD117, Dog-1, and S-100 were negative; Ki-67 labeling index was 30%." (PMID 39465747, 2024). "Alternative approaches include RNA interference and peptides targeting ERG, showing efficacy in reducing tumor growth in preclinical models." (PMID 38674385, 2024). "By contrast, in UF PCa, only the overexpression of ETV1 and ERG were related to high tumor stage and perineural infiltration, respectively." (PMID 38017230, 2024). "Association of the special histopathological variables with MVD by ERG expression in tumor and adjacent areas among patients with CRC." (PMID 38186453, 2023). "Patients appeared to be more likely to derive OS benefit from xentuzumab plus enzalutamide if tumour expression of ERG was low." (PMID 37537253, 2023). "In conclusion, T2E and ERG overexpression promote cell proliferation, survival, and angiogenesis while modulating tumor progression and aggressiveness." (PMID 37509339, 2023). "The TMPRSS2: ERG gene fusion is the most frequent genomic alteration in several tumour cases and results in overexpression of the transcription factor ERG." (PMID 37287057, 2023). "Immunohistochemically, the fibroblastic tumor cells consistently show diffuse ERG nuclear expression, which correlates with a significant ERG mRNA upregulation." (PMID 36983010, 2023). "TMPRSS2::ERG was the most frequent fusion in both cohorts, detected in 45% of FF_RP tumor samples and 28.6% of TCGA_PRAD samples." (PMID 37349736, 2023). "The common to European ERG fusions, including TMPRSS2‐ERG, were significantly under‐represented in African tumours (37.7% vs 13.3%, P = 0.0004), while private ERG (12 vs." (PMID 36629046, 2023). "While additional analyses would be needed to definitively assess clonality, this homogeneous ERG expression is consistent with the likelihood that this large tumor with heterogeneous mtDNAcn represents a single clonal origin." (PMID 37971875, 2023). "Unexpectedly, we also observed the presence of ERG-positive and CD34-negative spheroid-associated tumor cells." (PMID 37830603, 2023). "ERG immunoexpression was relatively homogeneous in all labelled tumor cells, of moderate to high intensity, and comparable to that of the internal positive labelling (endothelial cell nuclei)." (PMID 37894380, 2023). "ERG is an avian-vets member of the ETS family of transcription factors that plays a role in tumor angiogenesis and is effectively expressed in vascular endothelial cells, not stromal or tumor cells." (PMID 38186453, 2023). "Regarding KEGG analysis, the high‐ERG group was enriched in tumor‐progress‐related pathways, including signaling pathways regulating the pluripotency of stem cells, the HIF‐1 signaling pathway, and the Wnt signaling pathway." (PMID 37102261, 2023). "Analysis of somatic mutations or structural variants on a single-cell level will help confirm our identification of ERG- tumor cells and inform our understanding of their heterogeneity." (PMID 35013146, 2022). "Overall, we found 1244 genes significantly varied between ERG+ tumor cells and LE cells (FDR q < 0.01, Wilcoxon rank-sum test) while only 314 genes were significantly varied between ERG− tumor cells and LE cells (FDR q < 0.01, Wilcoxon rank-sum test)." (PMID 35013146, 2022). "Many tumor cells, both in primary tumors and in metastases, were growing in close proximity to ERG+ endothelial cells and formed a morphological foundation for angiocrine interactions." (PMID 36358614, 2022). "Our analysis shows that only 35.5% (321/904) of all tumor foci displayed ERG IHC staining and that 36.8% (165/449) of all tumor foci were ERG FISH positive." (PMID 35050902, 2022).
tumor (continued). "SLC45A3-ERG, identified in 2/115 (1.7%) tumours from African patients, after TMPRSS2-ERG is the second most common fusion event in ERG positive PCa tumours, while SLC45A3-ETV1 fusion has also been reported." (PMID 36045381, 2022). "We conclude that PGC1α silenced animals fail to initiate an ERG-mediated antioxidant response to metabolic stress resulting in ROS-mediated apoptosis and decreased tumor growth." (PMID 35508713, 2022). "Within the myeloid cells, we did not detect any significant composition differences in monocytes or macrophages between RP paired tumor and paired normal samples or between ERG+ and ERG− patients (P > 0.05, two-sided FET)." (PMID 35013146, 2022). "Our single-cell analysis reveals insights into the tumor immune microenvironment of localized prostate cancer based on ERG status." (PMID 35013146, 2022). "Of the 310 RP specimens (multifocal and unifocal) examined by dual ERG/SPINK1 IHC in all tumor foci, we identified collision tumors in 9.4% (n = 29) of patients." (PMID 35050902, 2022). "Of the 251 prostatectomy specimens harboring multiple tumor foci, ERG/SPINK1 IHC was performed on all foci in 233 (92.8%) specimens to be able to evaluate for interfocal heterogeneity." (PMID 35050902, 2022). "In our dataset, ERG + tumor cells were predominantly found in tumor samples while ERG− tumor cells were found in paired tumor and normal samples." (PMID 35013146, 2022). "Studies have documented that ERG plays a central role in PCa progression due to its ability to enhance tumor growth by promoting inflammatory and angiogenic responses." (PMID 35563163, 2022). "We repeated the pseudotime analysis in an unsupervised manner without specifying the starting point and the pseudotime trajectory was consistent that BE cells give rise to club cells, LE, and both ERG+ and ERG− tumor cells in our dataset." (PMID 35013146, 2022). "In PCa, SPOP was identified as a tumor suppressor, and SPOP was associated with the ERG protein stability and the growth and aggressiveness of PCa." (PMID 36275733, 2022). "Tumor cells in five patients were over 90% ERG− and over 90% ERG+ in two patients, Tumor cells in four patients harbored both types of tumor cells." (PMID 35013146, 2022). "We did identify 1 ERG+ focus (0.1%) with simultaneous SPINK1 expression within the same tumor cells in less than 5% of the focus." (PMID 35050902, 2022). "IL-1β blockade also suppressed the proliferation of tumor cells detected by lower Ki-67–positive staining and tumor angiogenesis presented by decreased expression of ERG." (PMID 35471938, 2022). "Fusion of the ETS gene results in the high expression of ERG or ETV1, and it is an important cause of prostate tumorigenesis and tumor development." (PMID 36289913, 2022). "Thirty-seven percent (37%) of the analyzed primary tumors (32/86) were ERG+ (defined as positive if any part of the tumor was positive), while only 27% (25/92) of the metastases were ERG+." (PMID 36358614, 2022). "Treatment of VCaP with several inhibitors showed that ERG serine phosphorylation was dependent on AKT and IKK kinases and mediates CXCR4 expression, a gene implicated in the interaction between tumor cells and the surrounding microenvironment." (PMID 35267426, 2022). "From the cell-state composition comparison, we observed three cell states with more than 400 cells each that were almost exclusively detected in the ERG+ tumor cells, with each cell state largely attributed to one specific patient." (PMID 35013146, 2022). "For our downstream analyses, we classified patients based on ERG status by annotating the five patients with almost exclusive ERG− tumor cells as ERG− patients and the other six patients (exclusive ERG+ tumor cells and mixtures) as ERG+ patients." (PMID 35013146, 2022).